EPCAM (epithelial cell adhesion molecule)
Diseases named in the same sentence as EPCAM in open-access papers (continued):
Sharing a sentence is not in itself a finding about the gene and the disease.
tumor (continued). "Owing to an extremely low level of CD24 positive cells in C666-1, only CD44, EpCAM and EpCAM/CD44-selected cells from C666-1 were evaluated for their tumour-initiating ability in NSG mice." (PMID 28959019, 2017). "A BsAb HEA125 × OKT3 co-targeting EpCAM on EpCAM+ tumor cells and CD3 on T cells mediated the interaction of tumor cells and T cells which resulted in the formation of an immune synapse and activation of T cell." (PMID 28931402, 2017). "FNAB tumor sample show slight changes both in the concentrations and where both EpCAM and CD44 are located throughout the tumor after 12 and 24-hour perfusions." (PMID 28085924, 2017). "To intravasate, tumor cells undergo the epithelial‐to‐mesenchymal transition (EMT), where they lose the EpCAM‐positive (EpCAM+) epithelial phenotype, acquiring invasive properties." (PMID 28700115, 2017). "Again the combination of EpCAM BiTE‐expressing EnAd, combined with exogenous T cells, gave dramatic cytotoxicity to the SKOV3 tumour cells, which showed strong induction of apoptosis when infected with EnAd‐CMV‐EpCAMBiTE, but not parental EnAd." (PMID 28634161, 2017). "As far as we know, the current study is the first that assessed EpCAM expression in lymph node metastases of UCC of the bladder compared to matched normal lymph nodes and the matched primary tumor." (PMID 28820475, 2017). "Identification of tumor cells in these spiked samples was achieved by staining the isolated cells for DAPI, CK and EpCAM." (PMID 29134128, 2017). "More importantly, EpCAM expression was commonly observed in ZFX‐expressing HCC cells from fresh frozen tumor sections by immunofluorescence staining, suggesting the co‐expression of ZFX and EpCAM within same cells of HCC specimens." (PMID 28156061, 2017). "The CD44, CD24, HER2, and epithelial cell adhesion molecule (EpCAM) expression on BT474 and SK-BR-3 tumor cells was assessed by flow cytometry as a function of tumor treatment." (PMID 27835865, 2017). "Therefore, monitoring of tumor EVs, and especially EPCAM, may have important value." (PMID 28968987, 2017). "Studies carried out on hepatocarcinoma cell lines suggest that the highest tumor-initiating activity is displayed by CD133+EpCAM+, compared to CD133+EpCAM− and CD133−EpCAM+ cell populations." (PMID 28930164, 2017). "In NR genome, promoters of the three tumor suppressors (RARB, CDH1, and EPCAM) were found to be almost exclusively unmethylated by methylation-specific PCR (MSP)." (PMID 28467809, 2017). "To answer this question, we made use of the liver explant model to assess the IHC expression of stemness markers EpCAM, CK19 and Sox9 in synchronous HCC tumor nodules." (PMID 28764740, 2017). "In this study, we assessed and compared the immunohistochemical expression of stemness markers EpCAM, Sox9 and CK19 in HCC tissues from a cohort of liver explant cases consisting of multiple tumor nodules." (PMID 28764740, 2017). "One tumor from the gut showed some similarity with RMC and high expression of EPCAM, an epithelial and carcinoma marker." (PMID 28427232, 2017). "Generally, we observed a trend of epithelial markers (EpCAM, CK18, CK19, EGFR) to be downregulated in CTCs compared to the bulk tumor cells derived from hepatic metastases, of these genes EGFR reached statistical significance (p = 0.019)." (PMID 27029058, 2016). "We first evaluated the simultaneous expression of EpCAM, CA9 and CD147 in serial sections of tumor specimens collected from the RCC patient cohort spanning 4 different clinical stages by IHC analysis." (PMID 27494883, 2016). "As a third technology, we used the EPISPOT assay, which is based on an EpCAM-independent enrichment method (i.e., leukocyte depletion) and enables the identification of viable PSA-secreting tumor cells." (PMID 28000772, 2016).
tumor (continued). "Several epithelial markers (EGFR, EpCAM, CK18, CK19) were downregulated in CTCs compared to the corresponding tumor tissue." (PMID 27029058, 2016). "It has been reported that exogenous miR-181 increased EpCAM+ HCC cell quantity and tumor-initiating ability." (PMID 27835990, 2016). "Previous studies have shown that EpCAM expression can be lost in epithelial tumor cells undergoing EMT and circulating tumor cells." (PMID 27611664, 2016). "Most of the tumor samples analyzed (> 90%) expressed very high levels of CA125, FOLR1, EPCAM and MUC-1 and intermediate levels of Her-2/neu, similarly to the OVCAR-3 cell line." (PMID 27323861, 2016). "Next, multicolor flow cytometry was used to evaluate the percentage of cells that were positive for CD24, CD44, EpCAM, CD133, and their combinations in three tumor-derived cell lines." (PMID 27414409, 2016). "As expected, most of the tumor samples analyzed (> 90%) expressed very high levels of CA125, FOLR1, EPCAM and MUC-1 and elevated levels of Her-2/neu, similarly to OVCAR-3 cell line." (PMID 27323861, 2016). "EpCAM high expression significantly had something to do with to age >60 years (p<0.001), upper parts of stomach (p=0.040), macroscopic type III (p=0.020), tumor size >7cm (p=0.002), T3 stage (p=0.017), N2-3 stage (p=0.019) and TNM III stage (p=0.004)." (PMID 27557490, 2016). "But, as expected double positive taMPs, EpCAM+CD147+ taMPs, were correlating with CRC tumour volume significantly (r = 0.7288, p < 0.0001, n = 43)." (PMID 27127176, 2016). "More than 90% of tumor samples expressed very high levels of CA125, FOLR1, EPCAM and MUC-1 and elevated levels of Her-2/neu, similarly to OVCAR-3 cell line." (PMID 27323861, 2016). "When the ALDHhigh population was further analysed as a percentage of the EpCAM+ population, ALDH activity was comparable with that observed in the original tumor samples." (PMID 25658706, 2015). "Similar to ALDFLUOR, we noted differences in the staining pattern of CD271/EpCAM between tumor and adjacent normal with poorly differentiated tumors showing higher levels of CD271+/EpCAM+ cells compared with differentiated tumors." (PMID 26311223, 2015). "HPCs/biliary markers including cytokeratin 7 (K7), cytokeratin 19 (K19), Epithelial cell adhesion molecule(EpCAM) and OV6 were stained in the HCC tumor tissues." (PMID 26311117, 2015). "PC3-luc tumor cells were injected into the tail vein of NOD/SCID mice and 6 h later PBLs transduced with EpCAM-specific CARs or control retroviruses were administered intravenously." (PMID 25636521, 2015). "The relapsing tumor has a larger proportion of CD44+ cells, than of CD133+ or EpCAM+ cells, making CD44 the most suitable therapeutic target." (PMID 25797268, 2015). "The enrichment of EpCAM+ cells in miliary patients could be explained by either a higher tumor cell density (with less stromal and infiltrating immune cells) or a more epithelial and less mesenchymal characteristic of the tumor cells (see transcriptomics data)." (PMID 25991672, 2015). "This indicates that PBLs transduced with the EpCAM-specific CAR can target and kill EpCAM+ tumor cells." (PMID 25636521, 2015). "The effect of EpApt-siEp construct on the expression of EpCAM and other CSC markers were studied between vehicle control and treated group (n = 2) tumor sections collected from day21 and day33 respectively." (PMID 26176230, 2015). "Unfixed slices were then labeled with fluorescently coupled anti-CD8 and anti-EpCAM antibodies to visualize CD8 T cells and tumor epithelial cells, respectively." (PMID 26528284, 2015). "Despite the low expression of EpCAM on PC3 cells, CAR-expressing PBLs significantly inhibited tumor growth and prolonged mouse survival in a PC3 metastasis model, probably by targeting the highly proliferative and metastatic population of cancer cells." (PMID 25636521, 2015).
tumor (continued). "In univariate analysis, tumor differentiation (p = 0.008), local progression (p = 0.001), lymph node metastasis (p < 0.001), clinical stage (p < 0.001), MTA1 and EpCAM high expression (p < 0.001) significantly predicted unfavorable overall survival." (PMID 26698569, 2015). "HCC with stemness-related marker expression is a recently proposed subtype of HCC in which a fraction of tumour cells (>5%) expresses stem/progenitor cell markers such as K19, CD133, c-kit, and EpCAM." (PMID 26110787, 2015). "Of the tested samples, 100% stained positive for NSE, 96% for CK20, 91% for CD56, 89% for ChrA, 72% for EpCAM, and 65% for MCV, confirming frequent expression of these MCC tumor markers." (PMID 26299616, 2015). "To examine the impact of p38 MAPK activation on tumor-initiating HCC cells, we conducted sphere formation assays on EpCAM+ HCC cells treated with DSF and/or SB203580, a specific inhibitor of p38." (PMID 24454751, 2014). "The CTCs were isolated by EpCAM enrichment, using an FDA-cleared automated platform (CellSearch) that quantifies the tumor burden in peripheral blood and provides data with predictive and prognostic value." (PMID 25593983, 2014). "This protocol also enables a detection of EpCAM-/CK- cells and epithelial-mesenchymal transition (EMT)-induced tumor cells using the incorporation of an EMT marker." (PMID 24886394, 2014). "Putative LCSCs (CD133+EpCAM+) were present in 6/7 tumor samples, and CD133+EpCAM+ cells were identified in the blood samples of 15 patients at a median level of 40/ml of blood." (PMID 23959111, 2014). "The same immunocytochemical staining strategy was applied to tumor tissues, and we phenotypically identified CD133+EpCAM+ CSCs in 36 % of the blood samples evaluated." (PMID 23959111, 2014). "MiR-181 was found to be upregulated also in CD133+, epithelial cell adhesion molecule (EpCAM)+, and AFP+ Tumor-Initiating Stem Cells (TISCs) by miRNA expression profiling in HCC." (PMID 24745023, 2014). "As we have shown, the majority of the established CR4 cells, as well as a significant proportion of cells from NOD/SCID mice tumor xenografts induced by these cells, express high levels of CD133, CD44, CD166, EpCAM and Lgr5." (PMID 24921652, 2014). "We then examined the expression of various markers of tumor-initiating HCC cells such as CD13, epithelial cell adhesion molecule (EpCAM), and CD133 using flow cytometry." (PMID 24454751, 2014). "In CTCs, cells are generally selected as EpCAM-positive and CD45-negative, which would miss any tumor cells with a mesenchymal phenotype." (PMID 25222669, 2014). "We also found that mTORC1 activation by BCAA treatment suppressed EpCAM-positive cells and enhanced the sensitivity of chemotherapeutic agents in HCC tumor." (PMID 24312415, 2013). "Exposure to serum-containing media induced the morphological differentiation of tumor spheroid cells into adherent monolayer cells, accompanied with the reduced percentage of CD133+/EpCAM+ cells (from 33.25 to 11.2%)." (PMID 23826249, 2013). "To confirm the inhibitory effect of metformin on the self-renewal of tumor-initiating HCC cells, we conducted immunocytochemical analyses of the expression of EpCAM and α-fetoprotein (AFP), hepatic stem/progenitor cell markers, in the resultant spheres." (PMID 23922888, 2013). "Immunostaining of the cancer stem cell markers in tumor cells revealed positivity for CD133, CD44, and EpCAM in the CLC." (PMID 23192764, 2013). "We examined the expression of EpCAM and CD133 using flow cytometry to analyze the effect of metformin on tumor-initiating HCC cells." (PMID 23922888, 2013). "Double staining showed that EpCAM and PCNA were co-expressed in numerous tumor cells, particularly in dysplastic ductal tumor cells." (PMID 23251255, 2013).
tumor (continued). "Beside CD133, markers such as CD24, EpCAM, CD166, Lgr5, CD47, and ALDH have been discussed and serve for the selection of tumour-initiating cells." (PMID 23150174, 2013). "In the primary patient tumor, the CD133+/EpCAM+ cell fraction only composed 4–6% of the total cell population." (PMID 23826249, 2013). "Comparable immunoreactivity for EpCAM was observed by immunostaining of HT29, Caco2 and SW480 cells in vitro and in corresponding tumours in vivo." (PMID 22590529, 2012). "Further investigations were performed on EPCAM, VEGFR and CD44, tetraspanins and integrins previously reported to participate in tumor progression by preparation of (pre)metastatic niche." (PMID 22768192, 2012). "Knockdown of EpCAM strongly reduced the invasion capacity of MCF-7 and T47D tumor cells in chicken tissue (yellow line and arrows)." (PMID 23110550, 2012). "The co-expression of EpCAM+CD44+, EpCAM+CD24+, and EpCAM+ABCG2+ ranged from 0.83% to 42.6%, 0.65% to 41.4%, and 1.6% to 6.5%, respectively, in the eight RB tumor samples." (PMID 22328825, 2012). "Several makers, particularly EpCAM and CK19 have been shown to correlate with more aggressive tumor behavior." (PMID 23216644, 2012). "By contrast, epithelium-like tumor cell lines MCF-7, T47D, and SkBR3 showed strong expression of the EpCAM protein as basic and glycosylated isoforms of 35 and 40 KDa." (PMID 23110550, 2012). "As our EpCAM IMS assay detected both hMAM +/- cells and CK +/- cells, this demonstrates that EpCAM is able to capture a broader range of tumor cells." (PMID 21816090, 2011). "Three tumour sphere cultures including two (cases 5 and 13) established from unsorted primary tumour cells and another expanded from the CD133+/EpCAM+ fraction isolated from case 11 were all sustained in culture for more than 5 months." (PMID 20332776, 2010). "Alternatively, the co-expression on tumour cells of CD44, CD166, and EpCAM molecules, has been reported to identify the CSC pool more precisely than CD133 expression alone." (PMID 20606680, 2010). "It has been reported that HCC probably originated from a few cancer cells that expressed certain tumour-initiating (TIC) markers such as CD133, CD90 and EpCAM." (PMID 20461085, 2010). "In contrast, EpCAM, IL8, CXCL10/IP10, CCL3/MIP-1α, CCL4/MIP-1β, CCL15/MIP-1δ, PDGFR-B were predominantly elevated in tumours compared to AN and PN." (PMID 21092330, 2010). "The result showed no significant change in the expression status (data not shown), suggesting that the chemoresistance induced by miR-21 is different from the relationship between the anti-tumour effect and IFNAR2 and EpCAM expression." (PMID 20978511, 2010). "Both, full-length EpCAM but also EpICD, which is composed of twenty-six amino acids only, rendered HEK293 cells tumourigenic in vivo and yielded large tumours with high efficiency after xenotransplantation in SCID mice." (PMID 19925656, 2009). "Expression of EpCAM on DTC and CTC, which are suspected to include early progenitor cells for metastases, is consistent with a role of EpCAM in tumour growth and progression, and stem cell fate." (PMID 17211480, 2007). "The trAb catumaxomab (removab®), which is based on the mAb HO-3 and displays specificities for EpCAM and CD3, is far more potent in inducing tumour cell killing by PBMC than is HO-3 alone." (PMID 17622246, 2007). "We have addressed this aspect, using monoclonal antibodies against two prominent antigens, EpCAM and HER2/neu that are frequently and independently expressed on micrometastatic tumor cells." (PMID 15771776, 2005). "By exploiting the expression of epithelial cell adhesion molecule (Ep-CAM) antigen, found on the surface of primary luminal epithelial and tumour cells, we have been able to obtain near homogeneity in purifications for both cell types." (PMID 12671707, 2003). "However, Doppel expression was significantly higher in tumor endothelial (CD31+; ±98%) than in epithelial (EpCAM+; ±78%) cells." (PMID 41317023, 2026).
tumor (continued). "Although EpAb3-5-detected EpCAM expression alone was not an independent predictor of overall survival (OS) or disease-free survival (DFS), its integration with tumor staging revealed a context-dependent prognostic association." (PMID 42038021, 2026). "Using flow cytometry to profile EpCAM and PSMA on circulating tumor cells (CTCs), we observed that Nonresponders displayed significantly higher EpCAM and lower PSMA levels than Responders, both at baseline and after the first treatment cycle." (PMID 41732759, 2026). "In HCC, tumor cells lacked EPCAM and expressed complement and stem cell markers; cancer-associated fibroblasts (CAFs) were scarce, and stellate cells expressed the pericyte marker RGS5." (PMID 41228323, 2025). "Staining patterns for all selected markers, including CEA, EpCAM, c-MET and EGFR, were predominantly heterogeneous in both tumor and adjacent normal epithelium, exhibiting intra- and inter-sample variations, whereas c-MET staining was mostly homogeneous (intra-sample variation) in normal tissues." (PMID 40563608, 2025). "Additionally, EpCAM signaling interacts with metabolic reprogramming to facilitate CSC adaptability and survival in adverse tumor microenvironments." (PMID 39996844, 2025). "Both 28 CAR and BB CAR demonstrated specific anti-tumor response against EpCAM positive tumor cells while remaining unresponsive to EpCAM negative controls." (PMID 41417221, 2025). "As the tumor cells dedifferentiate and increase EpCAM expression as they become more advanced, it is not unexpected that EpCAM fluorescence would be increased regardless of primary tumor histology." (PMID 41087662, 2025). "We compared GSN expression to adjacent sections of tumour stained for POSTN, α-SMA, CD3 and EpCAM." (PMID 40640495, 2025). "Transplantation of EpCAM+/CD45− cells into immunodeficient mice induces tumor formation, whereas EpCAM−/CD45− cells do not." (PMID 40791212, 2025). "Additionally, miR-181 was found to be upregulated in CD133+, epithelial cell adhesion molecule (EpCAM)+, and AFP+ tumor-initiating stem cells (TISCs) based on miRNA expression profiling in HCC." (PMID 41226441, 2025). "Our finding revealed that significantly higher expression of all four studied markers CD44, CD90, CD133, and EpCAM in HCC tumor tissues compared to corresponding non-tumor tissues (P < 0.05)." (PMID 40791212, 2025). "Meanwhile, we also detected the expression of EpCAM and CLDN3 in 16 tumor cell lines by RT-PCR." (PMID 40057807, 2025). "The cell isolated from patient sample #10 showed 80% EpCAM positivity after tumor cell purification using negative MACS selection." (PMID 40358156, 2025). "We assessed circulating tumor cell subsets expressing cancer stem cell markers (CD90, epithelial cell adhesion molecule, CD133, vimentin) using multiparametric flow cytometry at early and maximal response phases in patients receiving atezolizumab plus bevacizumab or lenvatinib." (PMID 40940925, 2025). "By leveraging label-free holographic morphology in conjunction with PSMA, the system is capable of identifying a broader spectrum of tumor cells, including EpCAM-low or EpCAM-negative populations." (PMID 40671945, 2025). "For detecting cells of potential tumor-origin in peripheral blood, we used the EpCAM marker, expressed on epithelial cells but not hematological cells." (PMID 40004014, 2025). "Specific proteins on exosomes, such as epidermal growth factor receptor (EGFR), Ephrin type-A receptor 2 (EphA2) and Epithelial cell adhesion molecule (EpCAM), are increasingly used to distinguish between tumor-derived exosomes and non-tumor-derived exosomes." (PMID 40612948, 2025). "Notably, the knockdown of miR-181 resulted in the reduced spheroid formation and tumor initiation capability, accompanied by the downregulation of cyclin D1 (CCND1) and epithelial cell adhesion molecule (TACSTD1) levels." (PMID 41514651, 2025).